AQP4 (aquaporin 4)
Diseases named in the same sentence as AQP4 in open-access papers (continued):
Sharing a sentence is not in itself a finding about the gene and the disease.
Stroke (continued). "Therefore, controlling the function of AQP4 is a potential effective target for treating post-stroke cerebral edema, although there is still a lot of research work to be done." (PMID 34483842, 2021). "In addition, we contributed to the current knowledge about the role of the GS in the pathology of stroke and the role of AQP4 in stroke." (PMID 34305569, 2021). "In line with this view, enhanced astrocyte activation observed in our HIF-1 LoF mice may also contribute to reduced injury as astrocyte aquaporin-4 expression facilitates reabsorption of vasogenic fluids from the extracellular space post stroke." (PMID 34046769, 2021). "The contribution of AQP4 varies greatly depending on time post-injury, brain region, amongst others leading to apparently contradictory results on edema, lesion size and outcome in AQP4 KO mice after stroke." (PMID 32523952, 2020). "Also, elevated expression of AQP4 was reported in the cerebral cortex of stroke-prone spontaneously hypertensive rat of 20 weeks and the spontaneously hypertensive rat of 32 weeks." (PMID 32397542, 2020). "Similarly, AQP4 labeling in the perilesion and contralateral cortex was decreased in Cav-1 KO mice compared to WT at 6 and 72h after stroke onset (red arrows)." (PMID 32523952, 2020). "AQP4 expression was rapidly up-regulated in the lesion and perilesion at 6 h in WT mice in agreement with our earlier description of an increase 1 h after stroke onset in the infarct core and ischemic penumbra." (PMID 32523952, 2020). "Considering the important role of AQP4 in stroke reperfusion injury, we speculated whether LncRNAs play an important role in regulating AQP4." (PMID 32138732, 2020). "Interestingly, the number of GFAP-positive processes correlated positively with perivascular AQP4 expression in WT animals after stroke but negatively in Cav-1 KO mice." (PMID 32523952, 2020). "Concomitant with the changes in AQP4 expression and coverage, reactive astrocyte morphological changes were severely diminished and brain swelling was increased in the Cav-1 KO mice after stroke." (PMID 32523952, 2020). "Altogether, increased perivascular AQP4 after stroke could be a protective mechanism by promoting edema resolution and facilitating water and debris clearance from the perivascular space." (PMID 32523952, 2020). "Treatment with thyroid hormone also reduced cerebral edema by inhibiting AQP4 and may be neuroprotective in patients with stroke." (PMID 33613264, 2020). "A significant increase in the length of perivascular-AQP4 staining was observed in the ipsilateral and contralateral cortex of WT stroke animals compared to WT sham (Tukey’s multiple comparisons test, 95% CI [−0.4949 to −0.1666], p < 0.0001 and 95% CI −0.3330 to −0.004702], p = 0.04 respectively)." (PMID 32523952, 2020). "In summary, Cav-1 appears to influence AQP4 expression and distribution along vessels contributing to changes in reactive astrogliosis and brain edema observed in Cav-1 KO mice after experimental stroke." (PMID 32523952, 2020). "Several studies have indicated that AQP4 expression is upregulated in the mouse model of stroke and brain edema could be moderated by downregulation of AQP4." (PMID 29599893, 2018). "The water channel AQP4 is enriched at astrocyte endfeet in the healthy brain but this polarization is lost in several neurological conditions including in Alzheimer’s disease and following stroke." (PMID 28826498, 2017). "Taken together, perturbed glymphatic pathway suggested by the aberrant dislocation of AQP4 water channel along with neuroinflammation may have contributed to the post-stroke amyloid deposit in M + B rats." (PMID 29121965, 2017). "HBO-PC has been observed to decrease brain water content and AQP4 expression in stroke models." (PMID 27438832, 2016). "Putative mechanisms of AQP4 modulation of cortical spreading depression (CSD) in stroke remain unclear." (PMID 25904843, 2015).
Stroke (continued). "AQP4 expression has been demonstrated to coincide with areas of glial-specific swelling, and their distribution is spatially and temporally regulated depending on the stroke model being employed." (PMID 25904843, 2015). "For instance, AQP4 inhibitors may be beneficial in the early course of stroke (cytotoxic phase) but potentially detrimental later on (vasogenic phase)." (PMID 25904843, 2015). "Because of its dual action, inhibitors or activators of AQP4 could theoretically be applied at different stages of stroke to exert specific actions." (PMID 25904843, 2015). "Aquaporin 4 (AQP4) is highly expressed in the glial cells of the central nervous system and facilitates the osmotically driven pathological brain swelling associated with stroke and traumatic brain injury." (PMID 26013827, 2015). "Different authors have observed that HS could down-regulate the expression of AQP4 in cerebral edema induced by stroke, bacterial meningitis or local cryoinjury." (PMID 23036239, 2012). "Old ApoE−/− mice with an elevated expression of AQP4 subjected to stroke might have a worse outcome with a higher degree of edema formation as previously proposed with AQP4 overexpression in transgenic mice." (PMID 22709928, 2012). "Modulators of AQP4 function, expression or perivascularclusteringmay therefore have a therapeutic application to reduce cytotoxic edema by blocking water influx in astrocytes at early stages of stroke." (PMID 21408176, 2011). "Previous studies using stroke and brain injury models have reported an initial AQP4 downregulation." (PMID 22011386, 2011). "Interestingly, AQP4 expression was rapidly regulated with a major induction 1h after stroke in astrocyte end-feet, indicating that early time points after the onset of the brain disorder should be considered." (PMID 21119881, 2010). "Studies demonstrating a role for AQP4 in relation to brain oedema in tumours, trauma and stroke as well as the observation that a small proportion of AQP4-null mice develop hydrocephalus, has also generated interest in the role of AQP4 in CSF circulation disorders." (PMID 20860832, 2010). "The role of AQP4 in handling brain water and therefore brain oedema has been demonstrated in several pathologies including cerebral tumours, traumatic brain injury, cerebral ischaemia or stroke and brain abscess." (PMID 20860832, 2010). "If one, for example, were to simply give an AQP4 blocker to stroke patients, timing would be critical; if given too early, it might reduce cytotoxic edema and tissue damage, but if continued too long, it could impair later edema clearance, worsening outcomes and becoming potentially fatal." (PMID 40943104, 2025). "Consequently, an ideal therapeutic strategy might involve AQP4 inhibition during the initial hours of stroke to mitigate cytotoxic edema, but AQP4 activation or restoration in later stages hastens vasogenic edema resolution." (PMID 40943104, 2025). "Thus, for the MCAO model, AQP4 in the transition area of the peri-lesion possesses the potential for plasticity and contributes to the recovery of the whole glymphatic function after stroke." (PMID 40837880, 2025). "Thus, by raising awareness about atypical presentations of NMOSD, such as vomiting and stroke-like symptoms, we would emphasise the importance of prompt brain contrast MRI imaging, along with serum and/or CSF for AQP4-IgG, for early diagnosis and treatment of similar cases in the future." (PMID 40772147, 2025). "Finally, region-specific changes in AQP4, particularly in white matter tracts and cortical networks, may also influence post-stroke recovery trajectories." (PMID 40564125, 2025). "Moreover, given the role of AQP4 in long-term outcomes (e.g., astroglial scar formation and post-stroke cognitive impairment via glymphatic dysfunction), modulating AQP4 might impact not just acute survival but also chronic recovery and dementia risk." (PMID 40943104, 2025).
Stroke (continued). "Thereby, higher baseline AQP4 levels might be protective against a stroke, indicating that this protein could independently predict good neurological outcomes and be used as a biomarker of neurological recovery in the acute-subacute phase of a stroke." (PMID 39596535, 2024). "Furthermore, multiple studies utilizing magnetic resonance imaging (MRI) have demonstrated that elevated AQP4 expression is temporally correlated with the resolution of edema in various pathological states, including stroke, traumatic brain injury (TBI), and neuroinflammatory lesions." (PMID 37762642, 2023). "During the early phase post-stroke, inhibiting AQP4 might help reduce cytotoxic edema." (PMID 38178909, 2023). "Moreover, targeting CaM to inhibit the cerebral edema mediated by AQP4 may provide a therapeutic target during the acute phase in a photothrombotic stroke model." (PMID 36769234, 2023). "However, the precise role of AQP4 polarization upon stroke induction is still under debate." (PMID 37554272, 2023). "Changes in astrocyte functions after stroke or in AD-related dementias could drive impaired perivascular clearance, either directly due to altered expression of AQP4 or other genes involved in this process or indirectly by altering vascular tone, and therefore contribute to AD." (PMID 34327206, 2021). "Therefore, lower perivascular AQP4 after stroke in cav-1 KO mice could be a consequence of decreased laminin." (PMID 32523952, 2020). "Interestingly, several genes such as GAD1, GJB6, GJD2, and AQP4 known to be induced or repressed by those early events of stroke are regulated in an opposite manner by PACAP which contributes to explain how PACAP protects the brain after stroke." (PMID 33551991, 2020). "This could account for why there is currently little consensus regarding whether AQP4 changes in expression levels is upregulated in animal models of stroke, as variations in the stroke model, the duration of reperfusion, and the methods used to determine AQP4 levels can all affect the outcome." (PMID 29326556, 2017). "Therefore, AQP4 inhibitors may be beneficial during the early stages of stroke, but could be deleterious if administered during the later stages when the clearance of water from the brain into the vasculature is crucial." (PMID 27438832, 2016). "Aquaporin 4 (AQP4) is a water channel protein expressed abundantly in the brain, especially in the perivascular astrocyte endfeet hypothesized to play a central role in the cerebral edema process in stroke as well as in TBI." (PMID 24705212, 2013). "Therefore, blocking AQP4 or inhibiting its clustering around blood vessels would reduce water entry which may be beneficial in preventing cytotoxic edema at early stages of stroke." (PMID 21408176, 2011). "Finally, clinical studies should incorporate AQP4-related endpoints, for instance, genotyping stroke patients for AQP4 SNPs or measuring AQP4 in biofluids to further validate AQP4 as a therapeutic target and stratify patients who might benefit from AQP4-directed treatments or classical treatments." (PMID 40943104, 2025). "By doing so, and by designing clever strategies to harness AQP4’s friend side while mitigating its foe side, we may significantly improve the management of brain edema, saving lives and improving neurological outcomes for stroke and brain injury patients worldwide." (PMID 40943104, 2025). "Only three studies evaluated the presence of other NSA-Ab seropositivity after stroke, finding very few patients with LGI, CASPR2, myelin, GAD65, MOG and aquaporin-4 antibodies, with a very similar rate in the control group." (PMID 39897448, 2025). "Together, our findings suggest that astrocytic upregulation of pH regulatory protein NBCe1 after stroke contributes to increased BBB permeability, reactive astrogliosis, inflammation, and perivascular AQP4 dysregulation." (PMID 40762246, 2025).
Stroke (continued). "Second, much of the mechanistic understanding of AQP4 function in stroke stems from preclinical rodent models, often employing young, healthy animals that may not fully replicate the pathophysiological heterogeneity of human stroke, especially in aged or multimorbid patients." (PMID 40943104, 2025). "In conclusion, the ALPS index can reflect changes in AQP4-mediated glymphatic pathway function, suggesting a significant decline in the hyperacute phase and a notable recovery in the early chronic phase, which may have implications for stroke therapeutic strategies." (PMID 40837880, 2025). "Aquaporin-4 (AQP4), the predominant water channel in the central nervous system, plays a paradoxical role in stroke-related brain edema, facilitating both the formation and clearance of excess fluid depending on the pathological context." (PMID 40943104, 2025). "In a stroke model induced by middle cerebral artery occlusion followed by reperfusion, it was observed that administering a V1AR antagonist decreased AQP4 expression in cytotoxic brain edema." (PMID 39944892, 2025). "We performed Western blotting on the protein lysates from the total extracellular vesicle (TEV) and ADEV aliquots to detect and quantify the AQP4 and GDNF in EV cargo from the stroke-related samples compared to the control group." (PMID 39596535, 2024). "Glymphatic function was investigated using TGN-020 to mediate AQP4 inhibition and was correlated with a reduction in brain edema post-MCAO in rats and promoting neurological recovery at 14 days post-stroke." (PMID 38253938, 2024). "AER-270, a small-molecule inhibitor of AQP4-mediated water permeability, has been shown to reduce brain swelling in models of both TBI and stroke, highlighting its therapeutic potential." (PMID 39768394, 2024). "Here, we demonstrated the presence of AQP4 and GDNF in ADEV cargo during the first month following stroke, expanding on our previous findings regarding the post-ischemic ADEV profile and the GFAP content of these vesicles." (PMID 39596535, 2024). "We also found that Storax has effects in decreasing the expression of Cav-1 and AQP4 and increasing the expression of Mfsd2a and PDGFR-β at 6 h after stroke." (PMID 35873558, 2022). "At 14 days post-stroke, we stained for BrdU and CD31, to label new endothelial cells, and aquaporin 4 (AQP4), which is localized to the endothelial aspect of astrocytic endfeet." (PMID 33910014, 2021). "The AQP family contains 13 different members, of which the expression levels of AQP1, AQP4, and AQP9 in rodent models and humans are upregulated after stroke." (PMID 34483842, 2021). "On the other hand, AQP4 knockout in mice revealed intact BBB structure, which resulted in significantly reduced mortality, infarction, and cerebral edema after stroke as well as improvement in long-term neurobehavioral performance." (PMID 34899367, 2021). "There is compelling evidence that the upregulation of AQP4 mediates BBB disruption in repetitive ethanol intoxication, stroke and TBI." (PMID 32878052, 2020). "This review examines the significance of relevant AQPs in stroke injury and subsequently explores neuroprotective strategies aimed at modulating AQP expression, with a particular focus on AQP4, the most abundant AQP in the central nervous system." (PMID 27438832, 2016). "Through immuno-histochemical and Western blot analysis, AQP4 expression was more pronounced in TPC mice than in saline-treated mice and this was correlated with reduced edema at 1 h post-stroke." (PMID 25904843, 2015). "Treatment with both doses of Neuroncell-EX showed lower expression of AQP4 in the cortex and striatum compared to stroke control albeit not statistically significant." (PMID 40360812, 2025). "Moreover, Nbce1iΔAstro stroke mice exhibited decreased blood-brain barrier (BBB) permeability, accompanied by preserved perivascular AQP4 polarization, upregulation of Kir4.1 protein expression, and reduced astrocyte domain volume." (PMID 40762246, 2025).
Stroke (continued). "Other studies have reported altered distribution of AQP4 after stroke such that it is no longer localised to perivascular end feet, potentially a response to the cellular influx of water that occurs during cytotoxic oedema." (PMID 40533800, 2025). "Clinically, no AQP4 agonists/antagonists are yet approved for stroke or edema; nevertheless, the converging evidence from human pathology, genetics, and biomarker studies suggests that AQP4 is a valid and potential translational target." (PMID 40943104, 2025). "AQP4 emerges not merely as a regulator of water homeostasis but as a multifunctional protein intricately involved in post‐stroke neuronal outcomes." (PMID 39444081, 2024). "There was a positive relationship between the severity of stroke at D1 according to the National Institutes of Health Stroke Scale, and ADEV AQP4 at D1 (r = 0.50, p = 0.031), as well as ADEV GDNF at D1 and D7 (r = 0.49, p = 0.035 and r = 0.53, p = 0.021, respectively)." (PMID 39596535, 2024). "In the present study, acute inhibition of AQP4 using TGN-020 decreased the edema and infarct lesion volume 1day post-stroke, attenuated peri-infarct astrogliosis, AQP4 depolarization, and infarct lesion volume, promoting neurological recovery at 14 days post-stroke." (PMID 35592320, 2022). "In the two experiments with Wistar rats, there was also an increase in laminin expression and in the number of activated microglia, together with a significant increase in AQP4 and GFAP levels in the stroke model compared with the AD plus stroke model at 24 h and up to 28 days later." (PMID 35743229, 2022). "We found that acutely inhibiting AQP4 using TGN-020 promoted neurological recovery by diminishing brain edema at the early stage and attenuating peri-infarct astrogliosis and AQP4 depolarization at the subacute stage after stroke." (PMID 35592320, 2022). "AQP4 is translocalized to the membrane by calmodulin-PKA pathway in astrocyte of rat CNS edema model, and trifluoperazine, a calmodulin inhibitor, ameliorates brain edema in acute phase stroke of a photothrombotic mouse model." (PMID 34948308, 2021). "In the most recent study, implementing photothrombic stroke model, TFP has downregulated AQP4 expression, reduced the amount of brain edema, and improved the metabolic function (as demonstrated via increased glycogen level of astrocytes located in ischemic penumbra)." (PMID 34966347, 2021). "This role was recently confirmed also in a photothrombotic stroke mouse model, where authors showed that administration of TFP during the early acute phase of stroke effectively reduced the cerebral edema and the AQP4 mRNA and protein expression levels in the brain." (PMID 34831273, 2021). "AQP4-labeling was absent in the striatum of Cav-1 KO mice at six but not in WTs, indicating a difference in AQP4 expression after stroke." (PMID 32523952, 2020). "Beyond, reactive astrocytes isolated from the brains of mice treated either with lipopolysaccharide or subjected to experimental stroke showed no increase in Aqp4-mRNA expression levels." (PMID 32998402, 2020). "We show now that mice lacking Cav-1 have significantly less astrocytic AQP4 in the lesion core, perilesion and contralateral cortex after stroke." (PMID 32523952, 2020). "Lower perivascular AQP4 expression was observed after stroke in absence of Cav-1, suggesting a role for Cav-1 in AQP4 expression in astrocyte perivascular end-feet." (PMID 32523952, 2020). "Following the onset of stroke, astrocytes keep changing their structure and function as indicated by the expression of GFAP and AQP4, which determine a conversion of the intracellular edema into extracellular edema in the lesion core while forming a shell of swollen astrocytes at the penumbra." (PMID 27242440, 2016). "When low-dose ethanol was administered to rats following an MCAO, a significant decrease in AQP4 expression was observed compared to the non-treatment stroke group." (PMID 27438832, 2016).